BRAF (B-Raf proto-oncogene, serine/threonine kinase)
Diseases named in the same sentence as BRAF in open-access papers (continued):
Sharing a sentence is not in itself a finding about the gene and the disease.
Langerhans cell histiocytosis (continued). "Vemurafenib, a BFAF inhibitor, has shown prolonged efficacy in patients with BRAF V600-mutant Erdheim-Chester disease (ECD) and Langerhans cell histiocytosis (LCH)." (PMID 40943476, 2025). "Vemurafenib was studied in nonmelanoma BRAF V600–mutant tumors, and preliminary activity was identified in NSCLC, Erdheim–Chester disease, and Langerhans cell histiocytosis, among other cancers." (PMID 38938274, 2024).
mucosal melanoma (76 papers, 2008 to 2026). A melanoma that arises from a mucosal site. "Unfortunately, mucosal melanoma presents activating BRAF mutations in 10% of the cases making these drugs useful in a low percentage of cases." (PMID 38920558, 2024). "These cases give warrant; a careful dermatological inspection should be instigated when confronted with a BRAF-mutated mucosal melanoma." (PMID 34142226, 2022). "The cutaneous lesion in our second patient was only removed because of the BRAF mutation in the patient’s mucosal melanoma instigated thorough dermatological investigation." (PMID 34142226, 2022). "The activation of BRAF mutations can be found in both skin (50%) and mucosal melanomas (10–20%) and can cause constitutive activation of BRAF and downstream MAPK signaling." (PMID 34178657, 2021). "BRAF mutations have been reported in 8% (107/1339) of mucosal melanoma involving V600E in 63% (67/107) and another codon in the remaining 37% (40/107)." (PMID 34571863, 2021). "A review about BRAF mutations collected in 1339 cases of mucosal melanoma revealed that BRAF mutations were present in 8.0% (107/1339) MM." (PMID 34044811, 2021). "This incidence is higher as compared to other mucosal melanoma, which harbor a BRAF mutation in only 12% of cases." (PMID 34071371, 2021). "In contrast to posterior UM and other mucosal melanoma subtypes, conjunctival melanoma quite frequently expresses BRAF mutations (~20–55% of patients)." (PMID 32718045, 2020). "Acral and mucosal melanomas more rarely harbor BRAF mutations (respectively, 10–15% and 5% of cases), which, on the contrary, have never been reported in uveal melanoma." (PMID 31683701, 2019). "KIT mutations were found in approximately 15% of acral and mucosal melanomas, and BRAF or NRAS mutation was found in approximately 10–15% of acral melanoma, but was less frequent in mucosal melanoma [8•, 9]." (PMID 30675668, 2019). "However, BRAF mutations are rare in mucosal melanomas, including tongue melanoma, limiting the applicability of these treatments." (PMID 40003600, 2025). "Notably, BRAF mutations are rare in mucosal melanoma compared to common cutaneous melanoma, so BRAF mutation testing is not recommended or reimbursed in some jurisdictions." (PMID 33431815, 2021). "However, BRAF V600E/K mutations are less common in mucosal melanoma, rendering them less amenable to BRAF/MEK inhibitor therapies." (PMID 31398831, 2019). "Molecular epidemiology studies indicated that the mutation pattern of mucosal melanoma is fundamentally different as compared to cutaneous locasion since KIT is the most frequently involved oncogene (15–25%) followed by a much less frequent involvement of BRAF, NRAS (<10%)." (PMID 31848942, 2020). "Indeed, the specific NRAS and BRAF mutants found in mucosal melanoma could be linked to their particular effects on protein activity during mucosal melanocyte transformation, adding an additional layer of complexity." (PMID 31398831, 2019). "The BRAF mutation rate was 27.2%, with significantly lower frequencies in ALM (8.5%) and mucosal melanoma (4.8%)." (PMID 40192945, 2025). "When BRAF V600E-mutant metastatic or unresectable mucosal melanoma (N = 12) patients were treated in a small study with BRAF inhibitors with or without a MEK inhibitor, the ORR was 20%, and DCR was 70%." (PMID 39001457, 2024). "These cell lines included samples from cutaneous, rare uveal, acral, and mucosal melanoma subtypes, including both BRAF mutant and wildtype lines." (PMID 34451846, 2021). "We catalogued alterations of the NRAS and BRAF genes in mucosal melanoma and showed that they represent a significant portion of mutations (20%) in these tumors." (PMID 31398831, 2019). "Similar to some cutaneous melanomas, BRAF fusions occur in mucosal melanoma, although they are rare." (PMID 31320640, 2019). "Mutations in mucosal melanoma are less common than in cutaneous or uveal melanomas and occur in descending order of frequency as: CKIT (20%), NRAS (5%) or BRAF (3%)." (PMID 25030020, 2014).
mucosal melanoma (continued). "BRAF V600E/K variants occurred in 22% of skin and 2% of mucosal melanomas, but not in uveal melanomas." (PMID 39823560, 2025). "When the mucosal melanoma is triple (BRAF, NRAS, NF1)-negative, KIT is the most commonly mutated gene in vulvovaginal melanomas, while APC and KRAS are detected mainly in sinonasal and anorectal melanomas, respectively." (PMID 34571863, 2021). "Cutaneous and mucosal melanomas share common mutations; however, the frequency of BRAF mutation is significantly higher arising in the trunk and skin without chronic sun damage compared to mucosal melanomas." (PMID 28443572, 2017). "For BRAF/NRAS wild-type PARM where immunotherapy access is limited, adjuvant temozolomide-cisplatin remains a clinically viable consideration, supported by prospective survival data in mucosal melanoma." (PMID 41458594, 2025). "The mutations of the KIT gene are found with greater frequency for mucosal melanoma (30%), unlike for BRAF and NRAS genes." (PMID 31274706, 2020). "A single exception has been recently reported concerning a case of metastatic mucosal melanoma harboring the GNAQQ209P mutation in exon 5, with no mutations of the BRAF, NRAS, or c-KIT genes." (PMID 25695059, 2015).
uveal melanoma (76 papers, 2003 to 2026). A melanoma derived from melanocytes of the uveal tract. "In CMs, uveal melanoma-related hotspot mutations appear to often co-occur with the mutations affecting the CM driver genes such as BRAF, NRAS, KIT, NF1, and ATRX." (PMID 37761808, 2023). "While immunotherapy, with ICIs, is regarded as a first line treatment for both mucosal and uveal melanoma, the lower frequency of BRAF mutations in these two subtypes means that BRAF inhibitors are of limited value." (PMID 35409020, 2022). "In contrast to cutaneous melanoma, mutations in BRAF are very rare in uveal melanoma, whereas mutations in GNAQ and GNA11 are common, and uveal melanoma has a much lower tumor mutational burden." (PMID 35021863, 2022). "B-Raf is the product of the oncogene serine/threonine kinase (BRAF), with gain of function mutations identified in uveal melanomas of humans." (PMID 35202299, 2022). "Genes that were known to be mutated in cutaneous and uveal melanoma subtypes, including BRAF, NRAS, NF1, GNAQ and GNA11, were rarely mutated in our cohort of patients." (PMID 30847022, 2019). "Uveal melanomas, in contrast to conjunctival melanomas, lack BRAF or NRAS mutations but frequently have mutations in GNAQ, GNA11, BAP1, SF3B1 or EIF1AX." (PMID 28938534, 2017). "Uveal melanoma was recognized as distinct tumor for a long time, and it is reflected in predominance of driver mutations in G protein subunits rather then BRAF or NRAS mutations." (PMID 24743024, 2014). "Using standard sequencing techniques BRAF mutations are not observed in primary uveal melanoma tumors, although two groups have identified BRAF mutations in a small number of primary uveal melanoma samples using more sensitive techniques." (PMID 24551032, 2014). "Though initial studies of uveal melanoma tumor samples reported that BRAF mutations are rare, several groups have detected the mutation in a disproportionate number of uveal melanoma cell lines." (PMID 22808163, 2012). "An alternative explanation is that this BRAF mutation is an infrequent event in uveal melanoma and the observed, inappropriate downstream activation of the MAPK component is due to genetic alterations in other components of this pathway." (PMID 18985043, 2008). "In this study, we performed mutation analysis of the RAS and BRAF genes in a panel of 11 uveal melanoma cell lines and 19 primary uveal melanoma tumours." (PMID 15928660, 2005). "We thus screened for activating mutations in the NRAS, HRAS, KRAS and BRAF genes in uveal melanoma cell lines and primary uveal melanomas." (PMID 15928660, 2005). "Although many uveal melanoma samples have been studied for BRAF and NRAS mutations, few have been analysed for MAPK activation and there is the implicit assumption that this pathway is not involved in uveal melanoma genesis." (PMID 15928660, 2005). "Moreover, the heterogeneity of our patient’s population (10% with brain metastases, 12% with mucosal or uveal melanoma, 20.9% treated with ipilimumab alone) and the exclusion of BRAF V600 mutated patients." (PMID 35382857, 2022). "We identified BRAF mutations in 21/74 (28%) patients, NRAS mutations in 4/74 (5.4%) patients, NF1 mutations in 1/74 (1.4%) patients and GNAQ mutations in 1/74 (uveal melanoma) (1.4%) patients, as well as BRAF/NRAS (1/74; 1.4%) and GNAQ/NF1 (1/74; 1.4%) double mutations." (PMID 32785074, 2020). "In addition, the uveal melanoma subtype usually lacks BRAF mutations, and with the exception of selumetinib, few data exist supporting the use of BRAF or MEK inhibitors in uveal melanoma." (PMID 28103611, 2017). "Based on the already recognised morphological and cytogenetic heterogeneity in uveal melanoma, we hypothesised that the BRAF mutation may be present in uveal melanoma but only in some of the tumour cells." (PMID 18985043, 2008).
uveal melanoma (continued). "However, there have been several studies, in uveal melanoma including primary and metastatic choroidal and ciliary body melanomas and the BRAF mutation has only been identified in one case." (PMID 18985043, 2008). "This makes BRAF an interesting candidate gene to screen in uveal melanoma tumours because of BRAF mutation being a potential mechanism for the activation of this pathway, and the fact that BRAF mutations are not thought to be related to the effects of UV light." (PMID 12778069, 2003). "Genomic patterns of BAP1mut non-uveal melanomas differed substantially from those of uveal origin in terms of mutational load and driver oncogenes: NF1, BRAF, and NRAS mutations were frequent, often with numerous co-mutations." (PMID 38903495, 2024). "In contrast, BRAF-mutant uveal melanomas likely harbor a deformed TSC1/2 complex resulting from inactivating TSC2 phosphorylation at Ser664 by hyperactive MEK and ERK60." (PMID 39349825, 2024). "Mutation analysis of tumor tissue revealed BRAF V600E/K mutation in 16 (64%), NRAS mutation in 2 (8%) and GNAQ or GNA11 mutation in 4 (n = 2, 8%; uveal melanoma; n = 2, 8%, primary CNS melanoma) patients." (PMID 36997799, 2023). "This is in line with previous works demonstrating metabolic adaptation after MAPK inhibition or CDK4/6i in BRAF mutant and uveal melanoma." (PMID 37420093, 2023). "In uveal melanoma, typically BRAF-wild type, the most frequent chromosome abnormalities, such as chromosome 3 monosomy and gain of chromosome 8q, demonstrated a prognostic value for relapse, but they did not predict response to treatment." (PMID 31683701, 2019). "Three of the BRAF WT patients had uveal melanoma; with these patients excluded BRAF WT patients had median PFS and OS of 8.0 months and 16.4 months, respectively." (PMID 30925943, 2019). "We have validated this in 151 cases of skin and uveal melanoma from our files, and correlated the data with PCR based assessment of BRAF status." (PMID 28228113, 2017). "Mutations in BRAF, KIT and NRAS are rarely seen in uveal melanoma; however more than 80 percent of uveal melanomas have mutations in GNAQ or GNA11." (PMID 26334521, 2015). "In order to assess the level of expression and the activation (by phosphorylation) of members of the MAPK pathway downstream of RAS and BRAF, Western blot analysis was performed on uveal melanoma cell lines." (PMID 15928660, 2005). "The frequency of BRAF mutations for each clinical subtype was as follows: ALM, 8.5%; SSM, 60.3%; NM, 46.8%; LMM, 26.9%; MCM, 4.8%; uveal melanoma, 0%; primary unknown, 25.5%; and others/unknown, 26.9%." (PMID 40192945, 2025). "There was one uveal melanoma patient with an exon 11 BRAF mutation who did not respond to treatment." (PMID 39207855, 2024). "In regard to target therapies, BRAF and KIT inhibitors are not included among treatment options, as uveal melanomas usually lack BRAF and KIT mutations." (PMID 34680428, 2021). "The combination of BRAF/MEK inhibitors is not possible due to the absence of BRAF mutations in uveal melanoma." (PMID 32532044, 2020). "Nearly half of patients with cutaneous and nearly all patients with uveal melanomas lack BRAF mutations, thus are not candidates for highly effective therapy with BRAF/MEK inhibitor combinations." (PMID 31615091, 2019). "Taken together, these studies demonstrate that MCL-1 downregulation is both necessary and sufficient to induce apoptosis with selumetinib, and strongly argues that MCL-1 is a singular target that is cooperatively modulated by the combination to induce apoptosis in BRAF mutant uveal melanoma." (PMID 22808163, 2012). "Therefore, we investigated the potential role of 4E-BP1 in AZD8055/selumetinib-induced apoptosis for BRAF mutant uveal melanomas." (PMID 22808163, 2012). "Despite the lack of mutations in the RAS and BRAF genes in this set of uveal melanomas, it is noteworthy that we observed phosphorylated (active) ERK1/2 expression in 10 of 19 tumours." (PMID 15928660, 2005).
uveal melanoma (continued). "Interestingly, activation of the MAPK and PI3K survival pathways is observed in uveal melanoma; however, driver mutations in BRAF or NRAS commonly present in cutaneous melanoma are not observed in uveal melanoma." (PMID 34533562, 2021). "It is known that uveal melanoma does not have a high frequency of BRAF mutations." (PMID 28573105, 2017). "In contrast, uveal melanomas did not exhibit mutations in BRAF and NRAS." (PMID 25280020, 2014). "This conclusion has significant ramifications for the development of rational therapies to treat uveal melanoma as it implies that general inhibitors of the pathway may still be effective even though the tumours do not have mutations of RAS or BRAF." (PMID 15928660, 2005). "Responses were seen in tumours harbouring BRAF fusions, GNA11, GNAQ, KRAS, NF1, and NRAS alterations, most frequently in low-grade serous ovarian cancer, central nervous system tumours, and uveal melanoma." (PMID 41664938, 2026). "Notably none of the tested mucosal or uveal melanoma were BRAF mutation positive." (PMID 34568037, 2021). "GNAQ and GNA11 mutations were common in uveal melanomas, while MAP-Kinase mutations were frequent in non-uveal melanomas with NF1, BRAF V600 and NRAS Q61 mutations occurring in decreasing frequency, consistent with a strong UV association." (PMID 38903495, 2024). "Instead, almost no BRAF mutations were observed in kidney chromophobe (KICH), acute myeloid leukemia (LAML), LIHC, TGCT, thymoma (THYM), and uveal melanoma (UVM)." (PMID 35910024, 2022). "Unfortunately, anti-BRAF therapy did not offer an alternative due to toxicity in both cutaneous and uveal melanoma." (PMID 36289768, 2022). "Although uveal melanoma does not express direct changes in the BRAF gene (rendering its indication of vemurafenib and dabrafenib unfeasible), it has mutations in the GNAQ or GNA11 (G protein subunit encoding) genes within 80% of cases." (PMID 28573105, 2017). "Interestingly, the downstream effectors of BRAF and NRAS, MEK, ERK and ELK, were constitutively activated in uveal melanomas." (PMID 25280020, 2014). "Our data revealed that while 4E-BP1 is cooperatively regulated by AZD8055/selumetinib, this is not critical for the induction of apoptosis in BRAF mutant uveal melanoma cells." (PMID 22808163, 2012). "This has implications for treatment, as BRAF inhibitors are now undergoing clinical trials from which uveal melanoma patients are unlikely to benefit." (PMID 12778069, 2003). "Given that PAK inhibition sensitizes mutant RAS- and BRAF-driven cell lines to the inhibition of the MAPK cascade, we hypothesized that PAK inhibition would also be able to sensitize GNAQ and GNA11 mutant uveal melanoma cells to MEK inhibitors." (PMID 41154654, 2025). "No BRAF, NRAS or NF1 mutations were detected in uveal melanoma samples." (PMID 38903495, 2024). "What remains unknown is how differences in uveal melanoma PTEN status may influence drug susceptibility independent of GNAQ and BRAF mutation status." (PMID 22808163, 2012). "However, it has been reported that mutations in BRAF and NRAS are absent in uveal melanoma." (PMID 35693877, 2019).